LEP (leptin)
Diseases named in the same sentence as LEP in open-access papers (continued):
Sharing a sentence is not in itself a finding about the gene and the disease.
Obesity (continued). "During the development of breast cancer, the capacity of proliferation (23.68% for MCF-7 and 17.24% for HCC1937), explained by the deregulation of leptin in obesity, could be very relevant at the moment of prescribing a treatment to the patient." (PMID 29311755, 2017). "Therefore, the Mc4r-deficient mice more closely reflect energy supply-driven obesity and allow studying hepatic changes found in NAFLD but leaving the leptin system genetically intact." (PMID 28207798, 2017). "Because the effects of Zn on leptin expression have been extensively reported, we asked whether Zn deficiency exacerbates and its supplementation attenuates HFD/obesity-induced cardiac alterations by reducing or increasing leptin levels." (PMID 28272348, 2017). "Key metabolic hormones, such as insulin, leptin, and adiponectin, have been studied extensively in obesity, however the pathophysiologic relevance of the calcitonin family of peptides remains unclear." (PMID 28666011, 2017). "Leptin concentrations may partly explain obesity's effects on thyroid status, perhaps through leptin's effects on TSH secretion." (PMID 28250769, 2017). "Furthermore, leptin treatment prominently reduced hepatic triglyceride accumulation and improved type II diabetes in clinical patients, clearly indicating a protective role of leptin against obesity and diabetes." (PMID 29312618, 2017). "Moreover, the inhibition of leptin signaling reduced Notch expression and development of breast cancer, which was more evident in obesity conditions." (PMID 27999190, 2017). "Obesity in this model seems to be related to overfeeding during development, possibly due to an imbalance in the hypothalamus between orexigenic and anorexigenic endocrine signals such as leptin and ghrelin." (PMID 30210555, 2017). "These modifications may indicate a feedback loop for the maintenance of leptin concentrations due to obesity." (PMID 28613268, 2017). "Indeed, obesity is characterized by accumulation of visceral adipose tissue that produces high quantities of inflammatory cytokines, mainly leptin, but also IL-1β, TNF-α, IL-8, and IL-6." (PMID 28182091, 2017). "The discovery of leptin in 1994 heralded the modern era of genetic and mechanistic obesity studies, providing the first direct evidence for a feedback loop, of sorts, that could control food intake." (PMID 28013339, 2017). "The results of the study support the existence of relationship among vitamin D, obesity and leptin in type 2 diabetic patients, which may indicate the role of leptin as a link between vitamin D status and type 2 diabetes." (PMID 29295491, 2017). "Additionally, it is well established that women with obesity have increased inflammation, circulating leptin concentrations, insulin resistance, lipolysis and dyslipidaemia." (PMID 28085991, 2017). "This is a very important pathway in obesity since increased circulating leptin levels lead to development of leptin resistance by chronic activation of JAK/STAT3 in the CNS, whereas in the peripheral organs chronic IL-6-induced JAK/STAT3 impairs insulin action." (PMID 29170528, 2017). "Conversely, patients with common obesity show high-circulating leptin and insulin levels." (PMID 28626772, 2017). "Leptin resistance is induced by the feeding of HF/HSD along with obesity." (PMID 28912580, 2017). "With the aim to gain a better insight into the relationship between obesity and breast cancer risk, we sought to clarify the contribution of individual adipokines (adiponectin, leptin, and IL-6 etc.) to obesity, and to provide a reference for breast cancer biomarkers." (PMID 29088874, 2017). "Therefore, in our in vitro studies, leptin concentrations of 10 or 100 ng/mL were used to simulate physiological as well as pathologically elevated leptin concentrations in obesity." (PMID 28357137, 2017). "Similarly, the abnormal production of leptin in obesity leads to leptin resistance and supresses insulin-stimulated glucose metabolism." (PMID 29021781, 2017).
Obesity (continued). "A plausible mechanism is suggested by the correlation between obesity and OA-like changes and plasma leptin concentrations but other hormones and cytokines released from macrophages may also be involved." (PMID 28418007, 2017). "Leptin has been suggested previously to represent a link between obesity and atherothrombosis." (PMID 29213245, 2017). "Thus, despite differences in the specific changes in each adipokine, the ADIPO:LEP ratio was altered in a similar fashion and the overall effect of these two obesity-targeted interventions on MCF7 cell proliferation was identical." (PMID 28873415, 2017). "In this study, protein stimuli was applied every 24 h in order to emulate the constant secretion of the said protein by adipose tissue in a condition of normal weight (10 ng/mL), excess weight-obesity (100 ng/mL), and a very high concentration of leptin (1000 ng/mL)." (PMID 29311755, 2017). "It has been well-established that obesity promotes leptin resistance." (PMID 28317846, 2017). "These significant relationships were ablated after further adjustment for BMI, indicating that the associations of these obesity-related loci with leptin were likely not due to gene pleiotropy." (PMID 29212175, 2017). "In particular, levels of leptin mRNA in subcutaneous fat were highly related with serum leptin level in high-fat diet induced obesity rats, and leptin secretion rates or mRNA levels of leptin in subcutaneous fats were highly correlated with the levels of serum leptin in women." (PMID 28934139, 2017). "Among obesity-related adipokines, leptin is likely to play a major role in cancer growth." (PMID 28708082, 2017). "Single gene alterations with Mendelian inheritance account for less than 5% of non-syndromic cases of severe EOO, including mutations in the LEP (MIM 164160) or LEPR (MIM 601007) genes, as well as in MC4R (MIM 155541) which are the most common cause of monogenic obesity." (PMID 28489853, 2017). "However, in obesity the large amount of leptin released by the adipose tissue leads to ARC neurons leptin insensitivity (also called leptin resistance) and contributes to food overconsumption." (PMID 29217834, 2017). "The data presented in this study support a novel hypothesis that leptin signaling in the pituitary plays a role in programming of increased adult offspring adiposity by maternal overnutrition/obesity." (PMID 28771488, 2017). "However, recent studies indicate leptin can also be synthesized in breast cancer cells in response to obesity-related stimuli." (PMID 28415788, 2017). "Together, these studies strongly support the implication of the epigenetic alterations of the leptin gene in the developmental programming of obesity, warranting further studies to examine its role in mediating the energy metabolic effects of maternal exposure to PM2.5." (PMID 28645299, 2017). "Interestingly, brain transcriptome analyses in this obese mice model identified several obesity-related pathways as leptin signaling." (PMID 28424580, 2017). "In other words, evidence suggests that leptin is a protein involved in the pathology of obesity." (PMID 28348585, 2017). "Leptin is a protein produced from the OB gen or “gen of obesity”." (PMID 29311755, 2017). "The most common genetic models of obesity are the ob/ob mouse and Zucker fatty rat, both of which harbor mutations in the leptin or leptin receptor gene rendering the hormone nonfunctional." (PMID 28466412, 2017). "The leptin (or obesity) receptor (ObR), which has six isoforms, is highly expressed in brain endothelial cells, astrocytes and tanycytes, and endothelial and astroglial cells have been studied in attempt to unravel the mechanisms of leptin transport into the brain." (PMID 28377744, 2017). "Hyperphagia and elevated levels of both insulin and leptin are common features of obesity." (PMID 28360931, 2017).
Obesity (continued). "We can speculate that impaired leptin signaling in the EMD mice may be responsible for mitochondrial disturbances suggesting a link between obesity and brain mitochondrial dysfunction, and further, mice learning impairments." (PMID 28143489, 2017). "Beside its link to obesity, leptin may also play a crucial role in cancer initiation, progression or in metastatic development." (PMID 28249041, 2017). "Higher plasma leptin concentrations (32.4 ± 4.1 versus 29.0 ± 4.4 mg/dL) and lower adiponectin levels (9.54 ± 1.33 versus 7.90 ± 1.08 μg/dL) were highlighted suggesting increased obesity-related complications." (PMID 28408969, 2017). "In obesity, serum adiponectin is decreased while leptin is increased." (PMID 28893239, 2017). "Moreover, the potential effect of overweight/obesity in salivary leptin-taste relationship was investigated." (PMID 28811937, 2017). "The severe obesity of ob/ob mice is attributable to hypothalamic hyperphagia; however, several studies have provided evidence for additional peripheral effects of leptin to modulate insulin sensitivity and metabolism directly in tissues, such as muscle and liver." (PMID 27899914, 2016). "The major anti-obesity effects of leptin are initiated by the phosphorylation of JAK2." (PMID 27812350, 2016). "Similarly, the side effects that LEP and LEPR share with selective serotonin inhibitors such as “food craving”, “binge eating”, “hyperphagia” and “obesity” suggest a connection between serotonin signalling and leptin." (PMID 27673331, 2016). "Overall, the decrease in leptin levels and in the leptin to fat mass ratio with birth weight suggest that the mechanisms by which low or high birth weight influence the development of obesity in later life might be different." (PMID 27141948, 2016). "This lead to the hypothesis; that reduction of hypothalamic MC4R signaling, shortly after initiation of a HFD, may explain the early onset of functional leptin resistance, which contributes, in part, to further manifestations of obesity." (PMID 27551276, 2016). "Leptin resistance is one of the mechanisms involved in the pathophysiology of obesity." (PMID 27746736, 2016). "Leptin and adiponectin are both obesity related regulatory proteins secreted by adipose tissue." (PMID 27247890, 2016). "A putative decrease in hypothalamic sensitivity to leptin may result in an inability to detect satiety despite the fat stores, which finally develop to obesity." (PMID 28082878, 2016). "Finally, “Leptin Signaling in Obesity” shows enrichment for genes detected within the top 1,000 for adjustment model 2 as well “Ephrin A Signaling” (B-H-adjusted p-values = 0.057)." (PMID 27019061, 2016). "Endoplasmic reticulum stress contributes to both leptin and insulin resistance in obesity." (PMID 27812350, 2016). "The link between obesity and cardiovascular damage may reside on leptin, since this peptide can increase sympathetic renal activity, reactive oxygen species (ROS) in kidney and reduce nitric oxide and that hyperleptinemia is a common feature in obesity." (PMID 27375501, 2016). "However, male heterozygous mice showed early onset leptin resistance, with a defect in leptin signalling in the hypothalamus, correlating with a mild, age-dependent obesity, insulin resistance and glucose intolerance." (PMID 27138914, 2016). "In addition, KBH-1 significantly improved the leptin-mediated signals impaired by obesity or FFA in the obesity model and primary cultured cortical neuron cells." (PMID 27618865, 2016). "In all of these models, reproductive dysfunction is at least partly attributable to loss of hypothalamic leptin signaling, rather than obesity per se." (PMID 27375552, 2016). "The relationship between leptin/LepRb, obesity and depression requires further study." (PMID 27739518, 2016).
Obesity (continued). "Thus, the occurrence of obesity in these models is basically owing to the abnormalities in leptin signaling, which result in hyperphagia (great desire on food), uncontrolled appetite, and reduced energy expenditure." (PMID 27708685, 2016). "The SNP rs7799039 of the LEP gene, when the A allele was absent, was associated with a higher frequency of obesity." (PMID 26880915, 2016). "Interestingly, deletion of Bardet-Biedl syndrome (BBS) proteins, known to promote LEPRb trafficking, impairs leptin signalling and results in leptin resistance and obesity, both in mouse models and in humans." (PMID 27138914, 2016). "Overall, whether leptin and adiponectin mediate the effects of low birth weight on obesity, insulin resistance and type 2 diabetes is unclear." (PMID 27141948, 2016). "Plasma leptin levels during and after pregnancy were associated with obesity class but not with degree of gestational weight gain." (PMID 27257506, 2016). "Existing data provide evidence that obesity may interfere with the neuroprotective effect of leptin on the brain, possibly by leptin resistance." (PMID 27547756, 2016). "In obesity, IL-1 and leptin production are increased while adiponectin production is decreased, which may be the reason that obesity increases breast cancer risk." (PMID 27609180, 2016). "Leptin has been suggested to play a role in the development of obesity related complications." (PMID 27257506, 2016). "Because leptin is crucial to the development of gastrointestinal malignancies and provides a link between obesity and tumorigenicity, a better understanding of the dysregulation of gastric leptin signaling and its role in obesity-induced gastric pathology is necessary." (PMID 26839577, 2016). "The involvement of gastric leptin in diet-induced obesity-associated gastric atrophy has not previously been investigated, although the elevation of serum leptin contributes to tumorigenesis in the stomach of obese mice infected with H. felis." (PMID 26839577, 2016). "The effect of leptin, a major regulator of body weight and food intake, is particularly evident in rodents and humans lacking a functional form of the protein, resulting in severe obesity and greatly increased appetite." (PMID 26904147, 2016). "Therefore, the purpose of this study was to investigate the effects of hypoxic living and exercise training on obesity and adipose tissue leptin/leptin receptor in dietary-induced obese rats." (PMID 27932989, 2016). "Unlike ob/ob mice, these double mutants were resistant to leptin deficiency‐induced genetic obesity because of increased energy expenditure." (PMID 27357657, 2016). "Thus, constitutive leptin production in encapsulated adipocytes was similarly efficient in improvement of glucose tolerance in mice with genetic or diet-induced obesity and insulin-resistance." (PMID 27055280, 2016). "In a first phase, a low energy dense diet as a consequence of fat restrictions, may decrease serum leptin concentration, thus programming compensatory metabolic responses promoting later obesity and leptin resistance." (PMID 27275827, 2016). "The accumulation of fat deposition and increase in adipocyte size in the body is a major characteristic of obesity, as well as an increase of leptin level processes of leptin resistance, which classically has been characterized by expansion of intra-adipose tissue." (PMID 27322312, 2016). "If leptin resistance is a major contributor to the etiology of obesity, it may be overcome in normal rodents, at least in part, by increasing hypothalamic leptin levels." (PMID 27579023, 2016). "Obesity could potentially alter the levels of multiple hormones and growth factors (e.g., testosterone, estrogen, leptin, insulin, and IGF-1) with competing effects on prostate growth and size." (PMID 27409334, 2016).
Obesity (continued). "In contrast to obesity-related metabolic abnormalities, lipodystrophy is associated with a lack of leptin and leptin replacement therapy has been shown to improve insulin resistance and hypertriglyceridemia in patients with lipodystrophy." (PMID 27649157, 2016). "Besides resistin, leptin is another increased physiological factor in obesity which also comes from adipose tissue." (PMID 27663646, 2016). "However, in obesity leptin levels significantly increase which then results in a functional state of leptin resistance, with impaired leptin action and a resultant decline in HP axis function." (PMID 27340554, 2016). "Our study suggests that adipose tissue from healthy subjects exerts antihypertrophic effects via an adiponectin–dependent pathway which is impaired in obesity, most likely due to adipocyte remodelling resulting in enhanced leptin and reduced adiponectin levels." (PMID 26731409, 2016). "The presence of obesity and hyperleptinemia in the LRbCre/Bbs1fl/fl mice prompted us to test whether these mice are leptin resistant." (PMID 26926121, 2016). "Therefore, the present study aimed to determine the modulation of leptin signaling molecule during the development of hepatic steatosis by a high-fat diet (HFD)-induced obesity model." (PMID 27618865, 2016). "Consequently, selective HDAC5 activation is a novel and promising approach to counteract leptin resistance and obesity by targeting the primary interactions between dietary challenges and the CNS control of metabolism." (PMID 26923837, 2016). "Hence, in this study, we assessed the associations between birth weight, markers of glucose homeostasis, obesity, leptin and adiponectin levels using a cross-sectional, population-based study conducted in Lausanne, Switzerland." (PMID 27141948, 2016). "Obesity-related elevation of TNFα may also be connected with the development of hyperleptinemia in obese subjects, because of leptin stimulation by TNFα." (PMID 27983705, 2016). "In fact, adiponectin may be a more responsive hormone than leptin, especially in patients with modest-obesity-induced insulin resistance." (PMID 27101398, 2016). "Finally, MVPA negatively influenced the leptin level in pubertal boys indicating a strong effect against adolescents’ obesity problem." (PMID 27439435, 2016). "Again leptin may play a key role in obesity related testicular dysfunction as leptin has been shown to inhibit the Leydig cell’s production of testosterone." (PMID 27340554, 2016). "Leptin is an anti-obesity hormone that attenuates food intake and enhances energy expenditure." (PMID 27746736, 2016). "However, we found that male PI3K-C2α KI mice displayed hypothalamic leptin resistance, leading to age-dependent obesity, insulin resistance and glucose intolerance." (PMID 27138914, 2016). "Similarly inhibition of hypothalamic Bdnf produces robust obesity, and Bdnf is stimulated by glucose and leptin." (PMID 27832201, 2016). "Growing evidence suggests that human milk may reduce the transfer of obesity from mother to progenies and leptin is one of the possible factors involved." (PMID 27338468, 2016). "Moreover, obesity, which is a known risk factor for NAFLD, has been associated with increased leptin levels." (PMID 27443391, 2016). "Furthermore, serum resistin and leptin have specific roles in the regulation of ATM in patients with modest obesity and early metabolic dysfunction." (PMID 27101398, 2016). "The ability of CNTF and its analogs to overcome leptin resistance in mouse models of obesity and in obese patients underscores its potential as an anti-obesity drug." (PMID 27445662, 2016). "Some studies indicated that diet-induced obesity may induce leptin resistance, a phenomenon characterized by elevated circulating leptin levels and decreased leptin sensitivity." (PMID 27534844, 2016).